DEK (DEK proto-oncogene)
Diseases named in the same sentence as DEK in open-access papers (continued):
Sharing a sentence is not in itself a finding about the gene and the disease.
gastric cancer (18 papers, 2014 to 2026). A primary or metastatic malignant neoplasm involving the stomach. "Some studies revealed that upregulation of DEK in patients with gastric cancer was associated with the presence of large tumors, serosal invasion, a poorer tumor grade, lymph node metastasis and increased stage tumors." (PMID 29228743, 2017). "We found that high levels of DEK expression were associated with poor prognosis in gastric cancer patients." (PMID 24650035, 2014). "In conclusion, DEK overexpression appears to be associated with gastric cancer progression, and DEK may potentially be used as a biomarker for prognostic evaluation and as a therapeutic target in gastric cancer." (PMID 24650035, 2014). "METTL3 mediates the m6A modification of DEK mRNA, which binds to the DEK 3’UTR through m6A, resulting in an increase in the stability of DEK mRNA and promoting DEK expression, promoting gastric cancer cell growth and metastasis." (PMID 39289775, 2024). "A study on the RBP DEK in gastric cancer cells has shown that DEK affects the selective splicing of a large number of cancer-related genes in gastric cancer cells, which are significantly enriched in pathways including cell apoptosis and cell cycle processes." (PMID 39726754, 2024). "It has been shown that DEK is highly expressed in gastric cancer tissues and cell lines, and the knockdown of DEK inhibits autophagy in cells." (PMID 38274803, 2023). "miR-138-5p targets FOXC1 and DEK to inhibit the progression of prostate cancer and proliferation of gastric cancer, respectively." (PMID 36005825, 2022). "The effect and regulatory mechanism of DEK on autophagy and apoptosis in gastric cancer (GC), and the role between miR-5100 and DEK or miR-5100 and LEF1-AS1 are still unclear." (PMID 35563178, 2022). "Our study found that DEK was highly expressed in gastric cancer tissues and cell lines, and knockdown of DEK inhibited the autophagy of cells, promoted apoptosis, and suppressed the malignant phenotype of gastric cancer." (PMID 35563178, 2022). "In this study, we found that METTL3 promoted the proliferation and migration of gastric cancer cells, and the knockdown of DEK reversed the effect of METTL3 on the proliferation and migration of gastric cancer cells." (PMID 35742899, 2022). "When we explored the mechanism of DEK overexpression in gastric cancer, we focused on the previously studied miR-5100." (PMID 35563178, 2022). "Our previous study showed that DEK inhibits apoptosis and promotes autophagy in gastric cancer, so we aimed at the molecular mechanism by which DEK exerts a tumor-promoting effect in gastric cancer." (PMID 35742899, 2022). "Up-regulated expression of DEK was related to many human diseases, such as uterine cervical cancer, gastric cancer, and neuroblastoma tumor." (PMID 32736520, 2020). "The positive rate of DEK protein expression was 70.3% (121/172) in gastric cancer tissues, which was significantly higher than that in either gastric dysplasia (41.7%, 15/36) or normal adjacent mucosa (18.5%, 5/27)." (PMID 24650035, 2014). "Both disease-free survival and overall survival rates were significantly higher in gastric cancer patients with low DEK expression than in those with high DEK expression." (PMID 24650035, 2014). "The strongly positive rate of DEK protein was 60.5% (104/172) in gastric cancers, which was significantly higher than that in either gastric dysplasia (19.4%, 7/36) or adjacent normal mucosa (0%, 0/27)." (PMID 24650035, 2014). "DEK expression in gastric cancer correlated to tumor size, differentiation, clinical stage, disease-free survival, and overall survival rates." (PMID 24650035, 2014). "DEK protein showed a strictly nuclear staining pattern in gastric cancers with IHC and immunofluorescence." (PMID 24650035, 2014). "We analyzed the relationship between DEK overexpression and clinicopathological features of gastric cancers." (PMID 24650035, 2014).
gastric cancer (continued). "Our results suggest the important role of DEK protein in the prognosis of patients with gastric cancer." (PMID 24650035, 2014). "This study aimed to investigate the clinicopathological significance of DEK overexpression in patients with gastric cancer." (PMID 24650035, 2014). "The strongly positive rate of DEK expression was significantly higher in gastric cancers with ≥5 cm tumor size (55/73, 75.3%) than in cases with <5 cm tumor size (49/99 49.5%) (P < 0.05)." (PMID 24650035, 2014). "We also observed that altered expression levels of DEK protein in gastric cancer tissues, which were significantly higher than both adjacent noncancerous tissues and normal stomach tissues." (PMID 24650035, 2014). "The expression of DEK protein was evaluated by immunohistochemical (IHC) staining of 172 gastric cancer samples with complete clinicopathological features, and the correlation between DEK expression and clinicopathological features was examined." (PMID 24650035, 2014). "This is the first study, to our knowledge, to correlate DEK levels in GAC with histological prognostic factors to understand the role of DEK upregulation in gastric cancer progression." (PMID 24650035, 2014). "DEK, in turn, promotes the proliferation and migration of gastric cancer cells." (PMID 41517663, 2026). "And to explore whether miR-5100 can regulate the autophagy and apoptosis of gastric cancer cells by affecting the expression of DEK." (PMID 35563178, 2022). "DEK protein showed a strictly nuclear staining pattern in gastric cancers with IF and IHC." (PMID 24650035, 2014). "Similarly, DEK expression was significantly higher in poorly differentiated gastric cancers (32/44, 72.7%) than in moderately (26/47, 55.3%) or well differentiated gastric cancers (46/81, 56.8%) (P < 0.05)." (PMID 24650035, 2014). "High level of DEK protein expression predicts the poor prognosis of patients with gastric cancer." (PMID 24650035, 2014). "Importantly, high DEK expression also emerged as a significant independent poor prognostic factor in gastric cancer (HR: 1.422, 95% CI: 1.033–1.956, P = 0.031)." (PMID 24650035, 2014). "METTL3 is involved in the m6A modification of the nuclear protein DEK, which improves the stability and expression of DEK, thereby promoting the proliferation and migration of gastric cancer (GC) cells." (PMID 41256854, 2025). "Also, miR-1292 inhibited gastric cancer cell growth, migration, and invasion via targeting DEK." (PMID 34594378, 2021). "Perhaps, the pathways regulated by DEK may represent a new strategy for cancer therapies and further study is also required to find out the exact signaling pathway regulated by altered DEK in gastric cancer progression." (PMID 24650035, 2014). "Additionally, serosal invasion, lymph node metastasis, and tumor stage were also associated with disease-free and overall survival rates, suggesting that DEK could be a valuable prognostic factor in gastric cancer." (PMID 24650035, 2014). "In the present study, we found that the expression of DEK was upregulated in gastric cancer tissues, and DEK might be an independent biomarker for the prediction of gastric cancer prognosis, suggesting that DEK plays an important role in the development and progression of gastric cancer." (PMID 24650035, 2014). "In conclusion, our results found that LEF1-AS1 and miR-5100 sponge function, and the miR-5100/DEK/AMPK/mTOR axis regulates autophagy and apoptosis in gastric cancer cells." (PMID 35563178, 2022). "In addition, the knockdown of DEK was found to reverse the effects of METTL3 on the proliferation and migration ability of gastric cancer cells, which was further verified by a lung metastasis model at the animal level." (PMID 35742899, 2022). "Nevertheless, DEK overexpression in gastric cancers was not related to age, gender, Lauren types and serosal invasion." (PMID 24650035, 2014).
gastric cancer (continued). "However, the expression status of DEK protein did not correlate to survival rate in patients with advanced stage (III–IV) gastric cancer (P = 0.255 and P = 0.137, respectively, log-rank)." (PMID 24650035, 2014). "However, the relationships between DEK expression and gastric cancer are not clear." (PMID 24650035, 2014).
melanoma (14 papers, 2007 to 2024). A malignant, usually aggressive tumor composed of atypical, neoplastic melanocytes. "Senescence-like phenotypes including proliferation arrest were induced in melanoma cells by the inhibition of oncogenic chromatin-remodeling factor DEK or microphthalmia-associated transcription factor MITF, a master regulator of melanocyte homeostasis and melanomagenesis." (PMID 23249808, 2012). "Thus, it will be of interest to test whether DNA damage per se or susceptibility to DNA damage caused by inhibition of DEK or MITF in melanoma cells are mediated by the depletion of dNTP pools, and whether upregulation of TS and RR suppresses these phenotypes." (PMID 23249808, 2012). "It is of note that the in vitro stable IFN resistance 11-core DEGs contained two melanoma oncogenes, SOX4 and DEK (transcription factors); the former was reported to be downregulated, while the latter was found to be upregulated during melanoma progression." (PMID 35269844, 2022). "Together, these data identify a new distinct link between a RBP (CELF1) and an oncogene (DEK) in the control of DNA synthesis and cell cycle progression modulators in melanoma." (PMID 29269732, 2017). "In melanoma, inhibition of DEK is sufficient to drive melanoma cells into senescence whereas overexpression prolongs cellular lifespan." (PMID 27057626, 2016). "DEK gene amplification and upregulated expression have been described in multiple cancer types including hepatocellular carcinoma, bladder cancer, and melanoma." (PMID 25340858, 2014). "Inhibition of DEK is sufficient to drive melanoma cells into senescence whereas overexpression prolongs cellular lifespan." (PMID 25216995, 2014). "It has been reported that MITF-depleted senescent cells activated the DNA damage response, whereas silencing of DEK increased sensitivity of melanoma cells to the DNA damaging agents." (PMID 23249808, 2012). "Furthermore, the oncogene DEK has been identified as a signal amplifier in this context, contributing to the progression of melanoma." (PMID 38443798, 2024). "Importantly, CELF1 and DEK were found to represent early-induced melanoma genes and adverse indicators of overall patient survival." (PMID 29269732, 2017). "Furthermore, additional RNA-immunoprecipitations demonstrated binding of CPEB4 to the 3′-UTR of BUB1B, CDK1 and DEK mRNAs in melanoma cells." (PMID 27857118, 2016). "Genomic gains of oncogenes like DEK are likely to be selected for because they confer a growth advantage to the malignancy, and 6p gains have been described in a number of malignancies including bladder and gastroesophageal cancer, osteosarcoma, and melanoma." (PMID 17397536, 2007). "Multiple studies have shown that DEK is upregulated in a variety of malignant conditions, such as acute myelocytic leukemia(AML), melanoma, hepatocellular carcinoma, retinoblastoma, urinary bladder cancer, glioblastoma, and oral squamous cell carcinoma (SCC)." (PMID 37664030, 2023). "Downregulation of BUB1B, CDK1 and DEK provides a mechanistic explanation for the aberrant spindles and defects in cytokinesis observed after sustained depletion of CPEB4 in melanoma cells." (PMID 27857118, 2016). "When the predictive power of all of these genes was tested on an ICI-treated melanoma patient cohort, 11 out of the 13 in vitro stable (containing IRGs SOX4, DEK, and HSPA1B) and AQP1 and CDCA4 in vivo stable DEGs were differentially expressed in the tumors of ICI responder melanoma patients." (PMID 35269844, 2022).
cervical cancer (11 papers, 2013 to 2022). A primary or metastatic malignant neoplasm involving the cervix. "In transformed cells, including Caski and HeLa cervical carcinomas, the loss of DEK by shRNA caused increased phosphorylation of IκBα." (PMID 26425120, 2015). "Previous studies have reported that silencing DEK inhibits the Wnt/β-catenin signaling pathway by mediating GSK-3β phosphorylation in cervical cancer." (PMID 33232276, 2020). "Similar to cervical cancer, DEK is upregulated in numerous head and neck cancers, regardless of HPV status." (PMID 32656741, 2020). "DEK overexpression has been implicated in the inhibition of cellular senescence, indicating that DEK plays a very important role in the progression of cervical cancer." (PMID 32656741, 2020). "This suggests that it might be important to investigate the relationship between HPV infection and DEK protein expression in cervical cancers, and further studies are needed to explore the mechanisms of DEK upregulation in the progression of cervical cancer." (PMID 32656741, 2020). "It has been confirmed in the cervical cancer cell that the expression of DEK was down-regulated, which could promote cell aging, while the exogenous overexpression of DEK could prolong cell life." (PMID 32041309, 2020). "DEK is a sequence‐conserved nuclear protein that regulates gene expression and is considered a potential therapeutic target and biomarker for various kinds of cancers such as breast cancer, lung cancer and cervical cancer." (PMID 33124760, 2020). "Another group showed that silencing of DEK led to downregulation of Wnt/β-catenin and MMP-9 in cervical cancer." (PMID 31766266, 2019). "It has been reported that DEK can be transcriptionally activated by the E7 oncogene, a classical negative regulator of the retinoblastoma (Rb) protein in human papillomavirus (HPV)-positive cervical cancer cells and primary human keratinocytes." (PMID 25544761, 2015).
leukemia (10 papers, 2014 to 2026). A malignant (clonal) hematologic disorder, involving hematopoietic stem cells and characterized by the presence of primitive or atypical myeloid or lymphoid cells in the bone marrow and the blood. "Altogether, these results identified a novel function of DEK::NUP214 as an XPO1-dependent transcriptional activator of key leukemia drivers and provide a rationale to explore the use of XPO1 inhibitors in this patient population." (PMID 40204893, 2025). "In this study, we determined DEK expression in different leukemia cell lines and found that DEK is highly expressed in Jurkat cells." (PMID 35769815, 2022). "Mice inoculated with PML/RARα- or DEK/NUP214-positive leukemic cells developed leukemia with a latency of approximately 4 weeks and a penetrance of 100%." (PMID 25568664, 2014). "We found that the L-IC of PML/RARα-positive leukemia is different from the L-MC, as already described for DEK/NUP214-positive leukemia." (PMID 25568664, 2014). "The cells originating from the PML/RARα-, RUNX1/RUNX1T1- or DEK/NUP214-positive LT-HSCs induced leukemia with a high penetrance of 70%, 50% or 80%, respectively." (PMID 25568664, 2014). "Intriguingly, this upregulation of HOX genes is shared with NUP98::NSD1, DEK (DEK proto-oncogene)::NUP214 (nucleoporin 214), and NPM1 (nucleophosmin 1) mutated cases, suggesting HOXA and HOXB overexpression is a common alteration in leukemia development." (PMID 37325571, 2023). "Although yet unstudied in the context of leukemia, a role for DEK in DNA-double strand break (DSB) repair may contribute to the poor response of patients to chemotherapy." (PMID 30669574, 2019). "Besides secondary mutations, disease progression in SET-NUP214- or DEK-NUP214-associated leukemia is certainly also influenced by the function of SET and DEK in their respective chimeric proteins." (PMID 30669574, 2019). "Recently, we showed that DEK/NUP214 initiates leukemia from LT-HSCs." (PMID 25568664, 2014). "We investigated whether activated STATs may mediate response to ATO treatment not only in PML/RARα but also in DEK/NUP214-positive leukemia." (PMID 25568664, 2014). "Thus, we hypothesized that DEK silencing might enhance the sensitivity of leukemia cells." (PMID 35769815, 2022). "DEK/NUP214 and PML/RARα exert their leukemogenic potential on a very small subpopulation of HSC explaining the low penetrance of leukemia from PML/RARα- and DEK/NUP214-transduced HSPCs." (PMID 25568664, 2014). "DEK/NUP214 and RUNX1/RUNX1T1 both induced leukemia with a low efficiency and long latency." (PMID 25568664, 2014). "In summary, these data show that the AAFPs PML/RARα and DEK/NUP214 initiate leukemia by transforming a small subpopulation of LT-HSCs, but both maintain already established leukemia from already committed cell populations in the BM suggesting a difference between L-ICs and L-MCs." (PMID 25568664, 2014).